GPX4 (glutathione peroxidase 4)
Diseases named in the same sentence as GPX4 in open-access papers (continued):
Sharing a sentence is not in itself a finding about the gene and the disease.
Psoriasiform dermatitis (2 papers, 2024 to 2025). A skin abnormality characterized by redness and irritation, with thick, red skin that displays flaky, silver-white patches (scales). "Psoriasiform dermatitis of K14/Gpx4 model is effectively treated with cytokine-directed immunoglobulins and ferroptosis inhibitors." (PMID 39570671, 2024). "Compared with normal lesions, lipid ROS and ferrous iron, the expression of acyl-CoA synthetase long-chain family member 4 (ACSL4) were increased, and the expression of GPX4 was decreased in psoriatic lesions, Fer-1 significantly suppresses ferroptosis and alleviates psoriasiform dermatitis." (PMID 40245702, 2025). "However, we also found that both KC ferroptosis and T cell responses triggered by ferroptosis are required for the maintenance of psoriasiform dermatitis in the K14/Gpx4 model." (PMID 39570671, 2024).
psoriasis vulgaris (2 papers, 2023). Plaque psoriasis is the most common presentation of psoriasis. "ROS and ferrous ions are increased in the epidermis of patients with psoriasis vulgaris, while glutathione peroxidases 4 (GPX4) is decreased." (PMID 38035065, 2023).
serous ovarian cancer (2 papers, 2023 to 2026). "This review examines the relationship between ferroptosis and chemotherapy resistance in high-grade serous ovarian cancer (HGSOC), analyzing the GPX4 antioxidant axis, polyunsaturated fatty acid biosynthesis, and iron homeostasis." (PMID 42231453, 2026).
synovitis (2 papers, 2022 to 2024). Inflammation of a synovial membrane. "In a lipopolysaccharide-induced synovitis model in one report, an increase in iron content and TFRC, as well as a decrease in GPX4, SLC7A11 and SLC3A2, was described, leading to increased cell death." (PMID 39513899, 2024). "A paper in 2021 showed that the iron content and the expression of TfR1 and NCOA4 in synovitis cells increased, while the expression of GPX4, SLC7A11, SLC3A2L, and NRF2 decreased in LPS-induced synovitis cell model, resulting in increased synovitis cells death and decreased cell viability." (PMID 35958605, 2022).
tendinopathy (2 papers, 2022 to 2025). "Taken together, the data indicate that FA inhibits ferroptosis in tenocytes through a GPX4‐dependent pathway, thus effectively alleviating the progression of tendinopathy." (PMID 35582962, 2022). "Additionally, farrerol alleviated tendinopathy by antagonizing GPX4 inhibition." (PMID 41573542, 2025). "Therefore, regulation of GPX4 may be important for the prevention and treatment of tendinopathy and the promotion of tendon healing." (PMID 35582962, 2022).
testicular germ cell tumor (2 papers, 2022 to 2025). A germ cell tumor arising from the testis. "However, GPX4 was downregulated in BRCA, LAML, and testicular germ cell tumors (TGCT) compared to normal tissues." (PMID 41142608, 2025).
tongue squamous cell carcinoma (2 papers, 2022 to 2025). A squamous cell carcinoma that arises from the tongue. "Evodia lepta extract selectively induces ferroptosis in tongue squamous cell carcinoma cells through GPX4 and HSPA5 downregulation, while simultaneously reducing PD-L1 expression, suggesting both cytotoxic and immunotherapeutic potential." (PMID 41227330, 2025). "Evodia lepta extract selectively induces ferroptosis in tongue squamous cell carcinoma by downregulating GPX4 and HSPA5, while simultaneously reducing PD-L1 expression." (PMID 41227330, 2025). "We found that tongue squamous cell carcinoma CAL33 expresses the highest level of GPX4 and the lowest level of HO-1 compared with other cell lines." (PMID 36012290, 2022).
toxoplasmosis (2 papers, 2025). A parasitic disease contracted by the ingestion or fetal transmission of toxoplasma gondii. "This study provides novel insights into the pathogenic mechanisms of T. gondii and identifies GPX4 as a regulatory factor that constrains parasite proliferation, offering new approaches for toxoplasmosis prevention and control." (PMID 40422259, 2025). "In this study, we found that T. gondii-induced tissue pathology is associated with reduced GPX4 expression and high expression of ACSL4, suggesting a key role of GPX4 and ACSL4 in mediating the pathogenesis of toxoplasmosis." (PMID 40667873, 2025).
abortion (1 paper, 2021). the ending of pregnancy by removing a fetus or embryo before it can survive outside the uterus. "By investigating rat abortion model, the results showed NLRP1 and NLRP3 expression in abortion rat uterus increased (∗P < 0.05, ∗∗P < 0.01), TFR1 and ACSL4 expression increased and GPX4 expression was decreased (∗P < 0.05, ∗∗P < 0.01), that compared with the control group." (PMID 34490257, 2021).
adenomyosis (1 paper, 2025). The growth of endometrial tissue inside the muscular wall of the uterine corpus. "Overall, our study provides evidence of ferroptosis in both the endometrium and myometrium of individuals with adenomyosis, characterized by reduced RNA m6A modification levels and diminished GPX4 protein expression." (PMID 40911580, 2025). "Ferroptosis has been identified in both eutopic and ectopic lesions of adenomyosis, which is characterized by low GPX4 expression." (PMID 40911580, 2025). "At the protein level, western blot showed that GPX4 was lowly expressed in the myometrial lesions of adenomyosis." (PMID 40911580, 2025). "Further MeRIP-PCR analysis on endometrial tissue from control and adenomyosis groups confirmed the downregulation of m6A-methylated GPX4." (PMID 40911580, 2025). "As anticipated, we confirmed that YTHDF1 can interact with GPX4, and the enrichment of GPX4 was reduced in adenomyosis." (PMID 40911580, 2025). "The western blotting results were consistent with human specimens, indicating a downregulation of METTL3 and GPX4 in adenomyosis." (PMID 40911580, 2025). "GPX4 may serve as a biomarker for evaluating the severity of adenomyosis." (PMID 40911580, 2025). "Immunofluorescence imaging demonstrated that the ectopic endometrium in mice exhibited lower expression levels of GPX4 and METTL3 in the adenomyosis group." (PMID 40911580, 2025). "In our research, we found that ferroptosis was present in both eutopic and ectopic endometrial tissues of individuals with adenomyosis by detecting changes in mitochondrial morphology, elevated MDA levels, an increased proportion of Fe2+ in total iron, and reduced GPX4 protein expression." (PMID 40911580, 2025). "GPX4 may serve as a biomarker reflecting the severity of adenomyosis, as it showed a significant negative correlation with CA125 levels, uterine size, and the severity of dysmenorrhea in patients." (PMID 40911580, 2025). "GPX4 may serve as a biomarker reflecting the severity of adenomyosis due to its significant negative correlation with CA125 levels, uterine size, and the severity of dysmenorrhea in patients." (PMID 40911580, 2025). "In our research, we found that GPX4 protein expression has negative correlations with CA125 levels, uterine size, and dysmenorrhea severity in adenomyosis." (PMID 40911580, 2025). "There was a significant negative correlation between GPX4 expression and CA125 levels, uterine size, and dysmenorrhea severity in adenomyosis." (PMID 40911580, 2025).
Age-related cataract (1 paper, 2024). A type of cataract (opacification of the lens) that forms during the course of aging. "A recent study reported that melatonin suppresses ferroptosis by regulating the SIRT6/p-Nrf2/GPX4 and SIRT6/NCOA4/FTH1 pathways in age-related cataract." (PMID 39519165, 2024).
Age-related cortical cataract (1 paper, 2023). A type of age-related cataract that primarily affects the cortex of the lens. "The downregulation of glutathione peroxidase 4 (GPX4), a key component of ferroptosis, was confirmed by real-time RT-PCR (RT-qPCR) and Western blotting in age-related cortical cataract (ARCC) samples." (PMID 38110879, 2023).
alcoholic hepatitis (1 paper, 2023). Acute hepatitis resulting from ingestion of alcohol. "In our study, by screening a miRNA library, we found that miR-214, which was significantly upregulated in the livers of alcoholic hepatitis patients, promoted ferroptosis in AML12 cells in the presence of GPx4 inactivation." (PMID 37626043, 2023).
alopecia (1 paper, 2024). Hair loss usually from the scalp. "Genetic deletion of Gpx4 (glutathione peroxidase 4), the main enzyme protecting cells from ferroptosis, in KCs induces dysmorphic HFs, focal alopecia and dermatitis in mice." (PMID 38649745, 2024).
anaplastic large cell lymphoma (1 paper, 2025). Anaplastic large cell lymphoma (ALCL) is a rare and aggressive peripheral T-cell non-Hodgkin lymphoma, belonging to the group of CD30-positive lymphoproliferative disorders, which affects lymph nodes and extranodal sites. "ML162 (a GPX4 inhibitor) treatment in FDFT1‐deficient ALK+ ALCL (ALK+ anaplastic large cell lymphoma) cells depleted squalene, damaging membrane PUFAs, key ferroptosis drivers, and generating lipid peroxides that induced ferroptosis." (PMID 40145543, 2025).
apical periodontitis (1 paper, 2025). "During the early phase of apical periodontitis, there is a response increase in the expression of GPX4 and SLC7A11 to protect the AP model from being damaged by ferroptosis." (PMID 39744165, 2025).
attention deficit-hyperactivity disorder (1 paper, 2014). A disorder characterized by a marked pattern of inattention and/or hyperactivity-impulsivity that is inconsistent with developmental level and clearly interferes with functioning in at least two settings (e.g. at home and at school). "Suppression of neuronal GPx4 expression resulted in a selective loss of parvalbumin-expressing GABAergic interneurons that are essential for dopamine-dependent regulation during attention and has been linked to attention deficit hyperactivity disorder (ADHD)." (PMID 24734177, 2014).
autism (1 paper, 2023). Persistent deficits in social interaction and communication and interaction as well as a markedly restricted repertoire of activity and interest as well as repetitive patterns of behavior. "For example, recent studies have shown that selenium can prevent ferroptosis by controlling the Nrf2/GPX4 pathway in the BTBR mouse model of autism." (PMID 37682882, 2023).
bladder tumor (1 paper, 2024). "The results suggested GPX4 was highly overexpressed in bladder tumor tissues compared with that in normal tissues." (PMID 38212623, 2024). "Therefore, immunohistochemistry (IHC) was performed to investigate the expression of GPX4 in bladder tumor tissues from 36 patients combined with normal bladder tissues from 18 patients." (PMID 38212623, 2024).
Blindness (1 paper, 2024). Blindness is the condition of lacking visual perception defined as a profound reduction in visual perception. "Conversely, in mice subjected to knockout of GPX4, an enzyme that scavenges oxidized lipids, retinal cell death occurs on postnatal day 21 leading to blindness." (PMID 38744193, 2024).
carotid atherosclerosis (1 paper, 2022). A thickening and loss of elasticity of the walls of carotid arteries that occur with formation of atherosclerotic plaques. "We suggest that ferroptosis of cells increases the expression of the IL-1B gene by inhibiting GPX4 and SIRT1, which activates the inflammatory response, produces a large amount of ROS, and finally leads to the occurrence of carotid atherosclerosis." (PMID 36393970, 2022). "Ferroptosis can lead to rapid lipid peroxidation of cells due to lack of GPX4, resulting in vascular endothelial cell damage and accelerating the occurrence of carotid atherosclerosis." (PMID 36393970, 2022).
cholestasis (1 paper, 2025). Impairment of the bile flow caused by obstruction within the liver, or outside the liver in the bile duct system. "To confirm that apoptosis is responsible for the death of Gpx4‐deficient hepatocytes in acute injury situations, we implemented a second ALI model triggering acute cholestasis." (PMID 40844245, 2025).
chronic liver failure (1 paper, 2025). Liver failure that develops slowly and gradually for some time, possibly for years, often as the result of cirrhosis, or malnutrition. "One expert pathologist determined a decrease in GPX4 levels in hepatocytes close to the injury site in ALF patients compared to control individuals and acute‐on‐chronic liver failure (ACLF) patients." (PMID 40844245, 2025).
chronic prostatitis (1 paper, 2022). An infectious or non-infectious chronic inflammatory process that affects the prostate gland. "Selenium, an essential component of GPX4 that confer resistance to ferroptosis, has been clinically applied in treating chronic prostatitis through inhibiting oxidative stress and inflammatory response." (PMID 35755168, 2022).
colonic benign tumor (1 paper, 2022). "The loss of Gpx4 in myeloid cells induced malignant progression in the AOM-induced colonic benign tumor model." (PMID 36970719, 2022).
congenital heart disease (1 paper, 2025). A heart disease that is present at birth. "In the congenital heart disease model generated by environmental pollutants (such as formaldehyde), PRMT1 was modulated by lncRNA 91,234.1, which influenced the expression of its downstream target ASCL4, subsequently regulating the expression of glutathione peroxidase 4 (GPX4)." (PMID 41256732, 2025).
dementia (1 paper, 2020). Loss of intellectual abilities interfering with an individual's social and occupational functions. "However, a case–controlled study on the association of GPx‐1 and GPx4 polymorphisms with episodic memory and AD in southern Brazil found that TT homozygotes showed a lower score for long‐term visual memory, but could be related to lower risk for dementia." (PMID 33070477, 2020).
demyelination (1 paper, 2025). "In addition, our results showed that FIS treatment significantly lessened MDA concentration and significantly augmented the GPX4 concentration in mice brain during de-and remyelination, emphasizing the antioxidant effect of FIS during CPZ-induced demyelination and fostering remyelination." (PMID 41361067, 2025).
disc degeneration (1 paper, 2023). "Moreover, using immunofluorescence to double label GPX4 and ubiquitin in discs, we found that the intensity of ubiquitin was increased and the expression of GPX4 was decreased in the puncture‐induced degeneration group, leading to further ferroptosis and disc degeneration." (PMID 36951540, 2023).
Down syndrome (1 paper, 2020). "ALDH inhibition has a synthetically lethal effect in AML cells when combined with glutathione peroxidase-4 inhibition, and it can overcome both bortezomib and cytarabine resistance in Down syndrome-associated AML." (PMID 33349623, 2020).
emphysema (1 paper, 2025). "Ferroptosis, marked by iron accumulation, glutathione (GSH) depletion, glutathione peroxidase 4 (GPX4) inactivation, and lipid peroxidation, is emerging as a key driver of airway epithelial damage, emphysema, and inflammation in COPD." (PMID 41252868, 2025).
Era (1 paper, 2025). "Consistent with Era treatment, ETEC infection decreased the expression of GPX4 and increased the mRNA levels of ChaC glutathione-specific gamma-glutamylcyclotransferase 1 (CHAC1) and solute carrier family 7 member 11 (SLC7A11)." (PMID 40867813, 2025).
esophagogastric junction adenocarcinoma (1 paper, 2025). "USP49 drives malignant progression of esophagogastric junction adenocarcinoma by activating the SHC binding and spindle associated 1 (SHCBP1)/β-catenin/glutathione peroxidase 4 (GPX4) signaling pathway." (PMID 41035649, 2025).
folic acid deficiency (1 paper, 2025). "In HT-22 cells with SLC7A11 knockdown, the expression levels of ferroptosis inhibitory proteins SLC7A11, GPX4, and FTH1 were significantly reduced, particularly under conditions of folic acid deficiency." (PMID 40724917, 2025).
gout (1 paper, 2024). A condition characterized by painful swelling of the joints, which is caused by deposition of urate crystals. "Studies have shown that GPX4 is closely associated with the occurrence and development of gout." (PMID 39606034, 2024). "ROC curve analysis revealed that the presence of ACSL4, VDAC2, and GPX4 in urinary exosomes possesses substantial predictive value for acute gout attacks." (PMID 39606034, 2024). "Moreover, ROC analysis in our study indicated that ACSL4, VDAC2, and GPX4 have strong predictive abilities for acute gout attacks, with AUC values of 0.771, 0.833, and 0.722, respectively." (PMID 39606034, 2024). "In conclusion, our study analyzed the expression changes of ferroptosis-related proteins ACSL4, VDAC2, GPX4, and GSS in the urinary exosomes of gout patients." (PMID 39606034, 2024). "Specifically, changes in ferroptosis-related proteins such as ACSL4, VDAC2, GPX4, and GSS may serve as promising biomarkers for the monitoring of acute gout attacks." (PMID 39606034, 2024).
gynecological malignant tumors (1 paper, 2022).
H1N1 virus infection (1 paper, 2024). "Western blotting showed a significant decrease in FTH1 and GPX4 protein expression levels after 24 hpi of PR8 H1N1 virus infection vs controls, which was consistent with ferroptosis characterization." (PMID 39159143, 2024). "In previous results, we observed a significant reduction in GPX4 protein expression with PR8 H1N1 virus infection." (PMID 39159143, 2024).